SCUBE2 (signal peptide, CUB domain and EGF like domain containing 2)
Diseases named in the same sentence as SCUBE2 in open-access papers (continued):
Sharing a sentence is not in itself a finding about the gene and the disease.
endometrial cancer (1 paper, 2022). Primary or metastatic malignant neoplasm involving the endometrium (mucous membrane that lines the endometrial cavity). "The study found a significant positive correlation between SCUBE2 transcription and PR and ERα, and PTEN expression might serve as a potential prognostic or predictive marker in endometrial cancer." (PMID 36142489, 2022).
medulloblastoma (1 paper, 2023). A malignant, invasive embryonal neoplasm arising from the cerebellum. "Given that HH signaling plays a critical role in maintaining cancer stemness and progression of various diseases, further investigations are needed to explore how SCUBE2–HH signaling is involved in the progression of human pathologies, such as SHH-subgroup medulloblastoma." (PMID 37237303, 2023).
vascular tumor (1 paper, 2022). "EC-specific Scube2-knockout (EC-KO) and SP.B1 (anti-SCUBE2 monoclonal antibody) inhibited vascular tumor density and xenograft tumor growth, increased apoptosis, and reduced tumor-cell proliferation in a mouse model." (PMID 36142489, 2022).
tumor (18 papers, 2009 to 2025). "SCUBE2 plays a pivotal role in sonic‐hedgehog (Shh) signalling, which is increased in luminal‐papillary, low‐risk, tumours." (PMID 32374509, 2020). "However in the present study, loss of SCUBE2 protein expression in the tumor epithelial component was the only marker significantly associated with lymph node status and borderline significant for DSS." (PMID 24885002, 2014). "Moreover, loss of SCUBE2 expression in different cancers is associated with pathological progression, in terms of clinical stage, tumor size, vascular invasion, lymph node status, depth of invasion and histological grade, and it is an independent predictor of poor prognosis." (PMID 37237303, 2023). "The first was a group of novel genes and the second was a group of genes associated with various cancer and tumour diseases (TXNDC12, NRDC, MIR761, ITSN2, NCOA1, SCUBE2, DENND5A, RCN2)." (PMID 40003092, 2025). "In contrast, SCUBE2, a protein with context‐dependent tumor suppressor functions, was found upregulated in HER2‐positive tumors in our analysis." (PMID 40488332, 2025). "In the earlier stages, SCUBE2 acts as a tumor suppressor, but is downregulated later during TGF-β-induced EMT." (PMID 37237303, 2023). "Together, these findings suggest that endothelial SCUBE2 is essential for angiogenesis that ensures tumor cell survival." (PMID 37237303, 2023). "The abnormalities in angiogenesis seen in Scube2-knockout mice suggest that tumor cells should become starved of nutrients and oxygen, leading to apoptosis and necrosis." (PMID 37237303, 2023). "We recently demonstrated that EC-surface SCUBE2 is an essential VEGFR2 coreceptor in the context of pathological tumor angiogenesis." (PMID 37237303, 2023). "The endothelial cell surface CUB and EGF-like domain-containing protein 2 (SCUBE2) is a coreceptor for vascular endothelial growth factor receptor 2 (VEGFR2) that is required for pathological tumor angiogenesis." (PMID 36718454, 2023). "Expression of the novel tumour suppressor SCUBE2 was significantly decreased in invasive regions compared to papillary regions (p < 0.05)." (PMID 32374509, 2020). "Our immunohistochemical assay illustrated that the protein level of SCUBE2 was significantly lower in tumor tissue than that in control." (PMID 31404982, 2019). "In several types of cancer, SCUBE2 is thought to act as a tumor suppressor." (PMID 37237303, 2023). "Also, SCUBE2 mRNA and protein were prominently upregulated in tumor tissues of the circ_SETD2 group compared to that in the vector group." (PMID 33336052, 2020). "Additionally, we also found a slight indication that UBE2C and SCUBE2, SERPINA11, and NME5 were associated with tumor differentiation (P = 0.06 and P = 0.09, respectively), inflammatory infiltration (P = 0.09), and p16 expression (P = 0.08), respectively." (PMID 24885002, 2014). "In addition, SCUBE2 was significantly associated with lymph node status (P = 0.01), CBX2 with tumor inflammatory infiltration (P = 0.03), and STK32B with tumor size (P = 0.04)." (PMID 24885002, 2014). "We found that CBX2, SCUBE2, and STK32B protein expression were associated with important clinicopathological features for OSCC (peritumoral inflammatory infiltration, metastatic spread to the cervical lymph nodes, and tumor size)." (PMID 24885002, 2014). "Therefore, an anti-SCUBE2 mAb that induces protein internalization may provide a powerful adjuvant treatment to block tumor angiogenesis." (PMID 37237303, 2023). "Nevertheless, our studies to this point have shown that SCUBE2 acts a crucial VEGFR2 coreceptor during tumor angiogenesis, and targeting SCUBE2 on the cell surface may be an effective anti-angiogenic treatment strategy that may be especially useful in combination with cytotoxic chemotherapies." (PMID 37237303, 2023). "Correspondingly, Scube2-knockout mice display increased apoptosis (TUNEL assay) and markedly lower levels of tumor cell proliferation (Ki67 immunostaining) compared to wild types." (PMID 37237303, 2023).
tumor (continued). "In particular, SCUBE2 regulates VEGFR2-mediated signaling in the context of postnatal ischemia-induced angiogenesis and also in hypoxic pathological tumor angiogenesis." (PMID 37237303, 2023). "In several clinical studies, SCUBE2 was found to be more highly expressed in non-metastatic tumor tissues than in normal tissues." (PMID 37237303, 2023). "However, hormone-related genes (BAG1, BCL2, CD68, ESR1 (ER), GSTM1, PGR, SCUBE2) do not show significant differential expression among all tumor samples." (PMID 38254834, 2024). "Since SCUBE2 is specifically upregulated by hypoxia and highly expressed in tumor vasculature, the anti-SCUBE2 mAb may provide a relatively nontoxic means of targeting tumor angiogenesis." (PMID 37237303, 2023). "Two main groups were identified, one over-expressing markers typically found in sporadic luminal tumours such as GATA3, TFF1 and SCUBE2, and the other negative for ESR1, ERBB2 and the PR gene (PGR) (triple negative) and over-expressing genes from the basal layer such as CDH3, CRYAB and KRT5-17." (PMID 19826428, 2009).
cancer (17 papers, 2013 to 2025). A tumor composed of atypical neoplastic, often pleomorphic cells that invade other tissues. "The subgroups include proliferation genes (Ki67, STK15; Survivin, CCNB1, MYBL2), invasion genes (MMPP11, CTSL2), HER2 genes (GRB2, HER2), estrogen genes (ER, PGR, BCL2, SCUBE2), and other cancer related genes (GSTM1, CD68, BAG1)." (PMID 33665165, 2020). "Finally, sheddases and the shedding regulator Scube2 are expressed in malignant tumors and can participate in the pathology of these cancers." (PMID 31018591, 2019). "The cancer genes are composed of genes that code for HER2 (HER2 and GRB7), oestrogen genes (ER, PGR, BCL2, and SCUBE2), proliferation genes (MKI67, STK15, BIRC5, CCNB1, and MYBL2), and invasion genes (MMP11 and CTSL2) as well as GSTM1, CD68, and BAG1." (PMID 36042999, 2022). "To support this idea, we compared Scube2-regulated release of recombinant Shh from Capan1, B16F10, Panc1, HeLa and MiaPaca2 cancer cell lines by using the strategy outlined earlier." (PMID 27199253, 2016). "Consequently, SCUBE2 and STK32B are involved in the hedgehog signaling pathway which plays a pivotal role in metastasis and angiogenesis in cancer." (PMID 24885002, 2014). "Although the roles of another four genes (SCUBE2, PRKCB, IKZF1, and MAP4K1) in NPC were not known, their functions were reported in other cancer types." (PMID 33403044, 2021).
infection (1 paper, 2017). The state of being infected such as from the introduction of a foreign agent such as serum, vaccine, antigenic substance or organism. "In CoMtb-stimulated BBB co-cultures, astrocytes had significantly lower levels of Scube2 than controls, which will reduce active Shh delivery to endothelial cells during infection." (PMID 29167512, 2017).
SCUBE2 also shares sentences with these, for which no sentence is quoted: dyslipidemia (2 papers); idiopathic pulmonary fibrosis (2); non-small cell lung carcinoma (2); bone metastasis (1); cardiovascular disorder (1); chronic pancreatitis (1); COVID-19 (1); endothelial dysfunction (1); Hyperglycemia (1); invasive breast carcinoma (1); lung carcinoma (1).